AXL (AXL receptor tyrosine kinase)
Diseases named in the same sentence as AXL in open-access papers (continued):
Sharing a sentence is not in itself a finding about the gene and the disease.
tumor (continued). "OPCML exerts its tumor suppressor effect by inhibiting several cancer hallmark phenotypes in vitro, and abrogating tumorigenesis in vivo, by downregulating/inactivating a specific spectrum of Receptor Tyrosine Kinases (RTKs), including EphA2, FGFR1, FGFR3, HER2, HER4, and AXL." (PMID 36835855, 2023). "In addition to regulating tumor growth, AXL also plays a key role in tumor-cell invasion." (PMID 36980768, 2023). "Moreover, AXL protein expression levels increased during HNSCC tumor progression." (PMID 35461210, 2022). "Tumor-associated myeloid cells exhibited higher transcriptional expression of molecules linked to the “find me” (G2A), “eat me” (CD93, TIM1, SCARF1, SLC2A1, GAS6, TREM2, AXL, C1QA), and downstream processing (NR1H3, ATG7, PPARG, ABCA1, PPARD, DOCK180) phases of efferocytosis." (PMID 36439171, 2022). "In addition, AXL inhibitors have demonstrated efficacy alongside anti-tumor vaccines." (PMID 35356198, 2022). "Thus, several studies now support the notion that AXL inhibition in vivo could lead to a reduction in tumor angiogenesis or a normalization of the blood vessels." (PMID 35158733, 2022). "Moreover, the detection of circulating tumor cells with MITF/AXL bias might help optimize prognosis and treatment." (PMID 35054460, 2022). "An elegant work using two immunocompetent syngeneic murine models of BCa (4T1 and E0771) has investigated how differential expression of AXL expression on tumor cells and MERTK on immune host cells could cooperate to promote immune evasion and immunosuppression." (PMID 35572601, 2022). "Beyond their potential use in preventing metastases in early stages of cancer, the evidence suggesting that AXL activity can keep the disseminated tumor cells dormant could provide a way to eliminate disseminated cells by making them less resistant to other therapies." (PMID 35158733, 2022). "In agreement with our hypothesis, we found that in metastatic lesions derived from gemcitabine treated mice the level of AXL phosphorylation (pAXL) in disseminated cancer cells was markedly increased compared with control (saline treated) metastatic tumour lesions." (PMID 35022267, 2022). "However, the underlying mechanisms by which AXL contributes to counteracting anti-tumor defenses are not yet fully understood and merit further investigation in several malignancies." (PMID 35572601, 2022). "Moreover, the molecular links between tumor cell plasticity, AXL expression, and resistance to immunotherapy remain unclear." (PMID 35572601, 2022). "Furthermore, the unique tumor microenvironmental conditions may modulate AXL and GAS6 expression in both tumor and immune cells to promote aggressive and pro-tumorigenic features." (PMID 34778071, 2021). "Finally, AXL was shown to be involved also in the immune regulation, thus having a potential role in mediating resistance to immune-checkpoint inhibitors or in creating an immunosuppressive tumor microenvironment permissive to tumorigenesis." (PMID 34745951, 2021). "Thus, the GAS6/AXL signaling is established and tumor cell dormancy is initiated." (PMID 34212564, 2021). "Furthermore, blockade of AXL has shown promise in preventing PDA tumor growth." (PMID 33497362, 2021). "Therefore, targeting AXL using inhibitors is a very promising strategy through both direct effects on cancer cells, and indirect effects via activation of APCs and a subsequent anti-tumor immune response." (PMID 31664482, 2020). "AXL overexpression may induce epithelial to mesenchymal transition, tumor angiogenesis, resistance to chemotherapeutic and targeted agents, and decreased anti-tumor immune response." (PMID 32448366, 2020). "The chi-square test indicated a significant association between AXL and c-ABL expression in the EAC samples (χ2 = 6.873, p = 0.032), and the expression of these proteins was significantly associated with EAC patient age (p < 0.001), tumor stage (p < 0.01), and lymph node status (p < 0.001)." (PMID 32922529, 2020).
tumor (continued). "Herein we propose that the inhibition of the actin cytoskeleton regulatory protein hMENA may interrupt the communication between cancer cells and CAFs leading to an inhibition of tumor invasiveness by regulating GAS6/AXL axis and impacts PDAC and NSCLC patient prognosis." (PMID 32909687, 2020). "Importantly, activating AXL with GAS6 stimulated tumour sphere formation and stemness." (PMID 32051483, 2020). "Collectively, these results establish the 3‐gene (ENAH, AXL and GAS6) expression signature as a prognostic indicator, hallmark of an aggressive disease in PDAC and LUSC patients and strengthen the clinical relevance of the hMENA expression pattern analysis in both tumor cells and CAFs." (PMID 32909687, 2020). "Collectively, the contact with extracellular matrix may lead to AXL overexpression in cancer cells and Gas6, secreted by some stromal cells, could induce the polarization of the Golgi toward the microenvironment allowing the escape of tumor cells." (PMID 31963783, 2020). "These comprised two truncating pathogenic variants—RB1 R255* and TSC1 R786*, one missense probable damaging variant—VHL tumor suppressor R58W, and four splice variants of unknown significance in ETS2 transcription factor, SGK1 serum/glucocorticoid regulated kinase 1, AXL RTK and MIB1." (PMID 31258848, 2019). "Our results reveal that AXL–GAS6 signal axis potentially has a key role in NSCLC tumor progression and survival prognosis; and AXL alone or in combination with GAS6 may serve as feasible biomarker for prognostic prediction in patients with metastatic NSCLC to the brain." (PMID 28551766, 2017). "Indeed, AXL expression was increased in tumours growing on BRAF inhibitor monotherapy." (PMID 28606996, 2017). "The use of this radioactive probe for noninvasive imaging of AXL, an important target for tumor metastasis and drug resistance, may provide valuable information about dose optimization, dose interval, and therapeutic efficacy for AXL-targeted molecular therapies." (PMID 29097911, 2017). "Moreover, we demonstrated that silencing AXL significantly inhibited the expression of proteins involved in the regulation of the extracellular matrix such as MMPs and uPA, unveiling the pathway by which AXL mediates tumor metastasis." (PMID 27764792, 2016). "In addition to hypoxia, nutrient deprivation within the tumor microenvironment may also contribute to the activation of GAS6/AXL signaling." (PMID 27834845, 2016). "However, when 5 × 104 cells (clone 2.2) were transplanted into the mammary fat pad of an immune-competent BALB/C host, AXL KO showed impaired tumor growth (50 % less tumor volume), which correlated with less metastasis (50 % less metastatic burden in the lungs)." (PMID 27595981, 2016). "Moreover, AXL was significantly co-expressed with genes associated with M2 macrophages, and positively correlated with the infiltration of CD163-positive M2 cells, suggesting an important relationship between AXL-expressing cells and TAMs with pro-tumor activity in a subgroup of TNBC." (PMID 28721387, 2016). "Moreover, they suggest that AXL could be a target for precision medicine approaches in this dismal tumor entity." (PMID 28025482, 2016). "In addition to tumor AXL expression, vascular AXL was also reported in ES samples." (PMID 25528764, 2014). "Therefore, combined treatment with EGFR and AXL inhibitors might effectively abrogate the growth of tumor cells." (PMID 24369725, 2013). "AXL and C-MET serve as important markers of tumor stem cell activity in CRC, providing prognostic information related to tumor aggressiveness, metastatic potential, and therapeutic resistance." (PMID 41563267, 2026). "Blockade of either AXL or GAS6 enhances NK cell activation, reduces metastasis, and promotes tumour control in breast cancer, melanoma, and pancreatic cancer models." (PMID 40948757, 2025).
tumor (continued). "In progressive PTC (stages II and III), nearly all tumor cells exhibited strong MERTK expression, while AXL expression remained unchanged between normal and tumor tissues." (PMID 40433916, 2025). "AXL-targeting drugs, including AXL tyrosine kinase inhibitors and AXL/GAS6 blocking antibodies, show promising antitumor activity through reshaping the complex tumor microenvironment (TME)." (PMID 40299452, 2025). "To determine the right combination therapy for controlling NSCLC tumors, we assessed the effectiveness of combining AXL and SRC inhibitors in regulating tumor growth using human cell lines and an animal CDX model." (PMID 39941857, 2025). "These miRNAs regulate tumour cell proliferation, migration, and immune evasion by participating in signalling pathways such as PI3K/AKT, MET/AXL, and Wnt/β-catenin." (PMID 41195336, 2025). "In the subgroup of patient tumour samples with an elevated accumulation of IL‐11, EMT genes (SNAI1, AXL and TWIST1) and hypoxia factor 1 (HIF1A) were over‐expressed compared with the subtype with a lower accumulation of IL‐11." (PMID 40673604, 2025). "TKIs such as cabozantinib, axitinib, and lenvatinib target critical pathways in angiogenesis, tumour growth, and metastasis, including VEGFR, MET, and AXL pathways." (PMID 40957947, 2025). "For instance, an AXL-CAR and AXL synNotch receptors engineered using humanized single-chain variable fragment (scFv) have demonstrated the ability to target and kill tumor cells." (PMID 39924521, 2025). "Since AXL/MERTK are mainly expressed in mouse Reg-TAMs, we conducted flow cytometry to examine tumor-infiltrated macrophages." (PMID 39774471, 2025). "Dual inhibition of AXL and SRC produced superior tumor growth inhibition (TGI ~70%) compared to either monotherapy." (PMID 39941857, 2025). "We found that FOXM1, AXL, and eEF2K are significantly overexpressed in GBM patient tumor samples and FOXM1 regulates the expression of AXL and eEF2K by physically interacting with these proteins." (PMID 40725039, 2025). "In mouse models, it significantly reduced tumor growth, especially in tumors with high MET and AXL expression." (PMID 41011010, 2025). "Clinically, the AXL–FAK axis represents a conserved driver of resistance and poor prognosis across multiple tumor types." (PMID 41462674, 2025). "Synergistic inhibition of AXL and SRC led to significant tumor growth suppression in A549 mice xenografts." (PMID 39941857, 2025). "Bemcentinib prevents AXL phosphorylation and downstream signaling in preclinical models of AML, resulting in reduced tumor growth, enhanced sensitivity towards therapy and enhanced anti-leukemic immune responses." (PMID 40122885, 2025). "We found that knockdown of AXL significantly reduced the expression of CCL-2, CSF-1, IL-10, and TGF-β cytokines in ccRCC tumor cells." (PMID 41029360, 2025). "Foretinib is an oral multi-kinase inhibitor targeting MET, ROS, RON, AXL, TIE-2, and VEGFR, which has demonstrated good anti-tumor activity and tolerability in a phase I/II single-arm study." (PMID 40376263, 2025). "AXL receptor tyrosine kinase (AXL kinase) plays a key role by upregulating PD-L1 expression on tumor cells, inhibiting NK cell activation, and supporting tumor survival." (PMID 40872475, 2025). "In TNBC, the GAS6-AXL signaling within cancer cells seem to foster cell survival, whereas in HER2BC, elevated GAS6 expression triggers pro-tumor AXL signaling." (PMID 41219968, 2025). "In addition, we verified ZAXL:239 affibody molecules, which significantly inhibited the proliferative activity of AXL-positive GC cells and found significant anti-tumor effects in AXL-positive GC transplantation tumor nude mouse models, which may be through MEK/ERK signaling pathway." (PMID 39644434, 2025). "Our studies confirmed that dual inhibition of AXL and SRC led to enhanced cell death and reduced tumor growth in both in vitro and in vivo models." (PMID 39941857, 2025).
tumor (continued). "We identified CCL8 as a critical mediator of the GAS6/AXL/MERTK pathway, primarily by inhibiting Treg infiltration into the tumor." (PMID 39774471, 2025). "One such driver is AXL, a receptor tyrosine kinase of the TAM family (TYRO3, AXL, MERTK), which has emerged as a critical regulator of tumor progression and immune evasion." (PMID 41009462, 2025). "Background/Objectives: AXL, a receptor tyrosine kinase of the TAM family, has emerged as a key target in cancer therapy due to its role in tumour growth, metastasis, immune evasion, and therapy resistance." (PMID 41471387, 2025). "AXL in GAS6 - AXL ligand-receptor pairs, implicated in HGSOC drug resistance, was exclusively expressed in HLA TAM1 and HLA TAM2, and only monocytes could communicate with tumor cells through ANXA1–FPR, which serve as effective mediators in controlling inflammatory responses." (PMID 40036264, 2025). "The presence of human CD3+ T-cells exclusively in the tumor tissues of the AXL-CAR-T cell group indicates effective targeting and anti-tumor activity." (PMID 40281554, 2025). "Discussions on signalling pathways have revealed specific mechanisms underlying the bidirectional regulatory effects of the TAM receptor family on tumours, of which PI3K/Akt and Gas6/AXL are two particularly critical signals." (PMID 40088262, 2025). "AXL facilitates the EMT and tumor invasion by turning on the mechanistic target of rapamycin kinase/Akt, Janus kinase/signal transducer and activator of transcription, nuclear factor-kB, and mitogen-activated protein kinase signaling pathways." (PMID 39590305, 2024). "Tumor samples from 111 NSCLC patients treated with ICI-monotherapy were analyzed by immunohistochemistry for tumor- and immune-AXL expression." (PMID 39238637, 2024). "GAS6/AXL is active also between START and tumor-enriched C25fibro (the major CAF subtype in EGFR-mutant ADCs) until treatment with Unesbulin stops it completely." (PMID 38546390, 2024). "The expression of two tyrosine kinase receptors, AXL and c-Met, was lower in parental populations treated with RAF inhibitors, reducing tumor aggressiveness when the cells were still sensitive." (PMID 39596009, 2024). "In this study, we demonstrated targeting AXL as a synergistic treatment in combination with WIN55212-2 by a significant reduction in cellular viability, colony formation and 3D tumor spheres, along with induction of the apoptosis of HCT-8 colon cells." (PMID 39598377, 2024). "ETS1 is a transcription factor and ETS1 gene expression correlates with AXL, IL6, and EFEMP1 in TNBC cell lines and tumor tissues." (PMID 38762181, 2024). "Phosphorylated AXL (pAXL), a receptor tyrosine kinase, promotes cancer progression, including epithelial–mesenchymal transition (EMT), tumor growth, and metastasis." (PMID 39597836, 2024). "AXL is a receptor tyrosine kinase that belongs to the TYRO3, AXL, and MERTK (TAM) family, which controls the tumor growth and EMT upon the binding of growth arrest-specific protein 6 (GAS6)." (PMID 39678497, 2024). "The negative correlation between AXL and immune infiltration was further validated using multiplex immunofluorescence staining of AXL, CD8α, and CD103 in TKI-treated murine tumor tissues." (PMID 38310091, 2024). "To validate the potential of modulating myeloid cells within the tumor to enhance antitumor efficacy, we combined DSP-0509 with an inhibitor targeting the receptor tyrosine kinase AXL." (PMID 39346737, 2024). "AXL inhibition potentiated the inhibitory role of WIN55212-2 on cell viability, colony formation and 3D tumor sphere, as well as the induction of apoptosis in HCT-8 cells." (PMID 39598377, 2024). "miR-122 acts as a regulator by inhibiting the β-catenin, AXL, and Rho A pathways to prevent the EMT and metastasis, and directly targeting TGF-β mRNA, reducing its effect, and helping to control tumor progression." (PMID 39590305, 2024).
tumor (continued). "AXL Hscore trended higher in patients with ECOG PS 2-3 vs ECOG PS 0-1 (P = 0.052) and positively correlated with initial tumor size (P = 0.043)." (PMID 39238637, 2024). "The gene AXL, belonging to the Tyro3-Axl-Mer (TAM) receptor tyrosine kinase subfamily, has the ability to enhance tumor advancement and serve as an indicator of unfavorable prognosis." (PMID 38194709, 2024). "The overexpression of AXL, a TAM receptor, together with growth arrest-specific 6 (GAS6), an antiapoptosis and pro-cell growth ligand, promotes tumor cell invasion in various malignancies, including HCC." (PMID 39590305, 2024). "Subsequently, we demonstrated that inhibition of AXL by TP-0903 potentiated the inhibitory role of WIN55212-2 on cellular viability, colony formation and 3D tumor sphere in HCT-8 cells." (PMID 39598377, 2024). "Although TKI drugs inhibit downstream signaling pathways of driver genes, key signaling pathways within tumor cells can still be persistently activated through bypass routes such as MET gene amplification, EGFR gene amplification, and AXL activation." (PMID 39582541, 2024). "Therefore, AXL might be a key mediator in the tumor malignant microenvironment." (PMID 37265798, 2023). "The present section mainly summarizes the cell-dependent role of Gas6/AXL in the TME in malignant cells, e.g., the roles of immune and vascular smooth muscle cells (VSMC) on tumor development." (PMID 37265798, 2023). "It is established that the IgLON family member OPCML acts as a tumor suppressor by eliciting the downregulation or the inhibition of RTKs, such as EphA2, FGFR1, FGFR3, HER2, HER4, and AXL." (PMID 37765276, 2023). "Gas6/AXL signaling activates Src, local adhesion kinase (FAK) and NFκB to promote proliferation in nerve sheath tumor cells." (PMID 37265798, 2023). "Low NCOR2 mRNA expression is positively correlated with shorter OS in LUAD patients, and downregulating NCOR2 promoted the expression of the tumor factors ELK1 and AXL." (PMID 38077434, 2023). "In retrospective analyses, selected cancer-associated mutations and alterations that are putative targets of sitravatinib in vitro (e.g., RET, MET, CBL, AXL, KDR, and NTRK) were monitored from circulating tumor DNA in baseline plasma samples (n = 49)." (PMID 36842467, 2023). "AXL is a direct target of HIF-2α and its overexpression correlates with ccRCC tumor invasion and metastasis." (PMID 36831657, 2023). "Sitravatinib, a receptor tyrosine kinase inhibitor targeting TYRO3, AXL, MERTK receptors, and vascular epithelial growth factor receptor 2, can shift the tumor microenvironment toward an immunostimulatory state." (PMID 36842467, 2023). "In the context of EGFR–driven lung tumorigenesis, MIG6, an EGFR–negative regulator, acts as a tumor suppressor by downregulating EGFR signaling, highlighting the emerging research focusing on the interplay between AXL, MIG6 and EGFR in NSCLC." (PMID 37834326, 2023). "Consistently with the genetic knockdown study, soluble AXL treatment reduced AXL activation (phospho-AXL and phospho-AKT) and tumor-cell survival in a dose-dependent manner." (PMID 36980768, 2023). "In vivo pharmacologic inhibiting pan-TAM Tyrosine Kinases, TYRO3, AXL, and MERTK, diminishes MDSC suppressive capability, promotes CD8+ T cell infiltration, slows tumor growth, and augments anti-PD-1 immunotherapy." (PMID 36823234, 2023). "Preclinical studies indicated that CAR-T cell therapy targeting AXL induced in vitro cytotoxicity in triple negative breast cancer cells (TNBC) and reduced tumor growth in a TNBC xenograft mouse model." (PMID 37469409, 2023). "Seven hub genes (AXL, EFEMP2, VIM, EHD2, FSTL3, ALOX5, HSPB8) were downregulated in tumor samples, while COL3A1 was upregulated in tumor samples in the TCGA dataset." (PMID 37291533, 2023). "The increased expression of AXL and GAS6 proteins was correlated with less differentiated histological grading, tumor stage and lymph nodes involvement." (PMID 37469409, 2023).